BTLA (B and T lymphocyte associated)
Diseases named in the same sentence as BTLA in open-access papers (continued):
Sharing a sentence is not in itself a finding about the gene and the disease.
tumor (continued). "The findings of the authors suggest that combined chemotherapy with BTLA blockade enhances immune activation and generates potent anti-tumor effects." (PMID 38233898, 2024). "In HNSCC, BTLA expression was shown to be significantly decreased in tumor-infiltrating T-cells compared with circulating T-cells." (PMID 38928307, 2024). "They discovered that BTLA can be expressed on tumor cells, being primarily detected in the membrane and cytoplasm of cancer cells and occasionally on TILs." (PMID 38233898, 2024). "BTLA expression in tissue should give us more information about immune parameters of the tumor microenvironment (TME) as ICI response rates strongly depend on the characteristics of the TME." (PMID 38928307, 2024). "BTLA is highly expressed in tumor cells of NSCLC patients, which is significantly positively correlated with high levels of PD-L1 and can predict the poor prognosis of NSCLC patients." (PMID 36308553, 2023). "This highlights the importance of HVEM as a ligand for the co-inhibitory receptor BTLA in the modulation of the anti-tumor responses." (PMID 37033927, 2023). "In fact, BTLA signaling disruption in vitro increased the proliferation and cytokine production in tumor-specific CD8+ T lymphocytes." (PMID 37649037, 2023). "Several investigations have revealed that BTLA plays a role in various pathogenetic processes, including tumor development, inflammatory diseases, autoimmune disorders, and graft failure." (PMID 37684436, 2023). "It seems that the deficiency caused by the lack of HVEM expression and the subsequent inability to co-inhibit T cell responses through BTLA provides the immune system with a competitive advantage to curb tumor growth." (PMID 37033927, 2023). "It has been shown that HVEM is the ligand of BTLA, and the ligation can lead to the inhibition of T cell activation and immune escape of tumor cells." (PMID 36552785, 2022). "Altogether, these data suggest that tumor cell-intrinsic BTLA is a potential tumor suppressor that deregulates the ERK1/2 signaling pathway." (PMID 36552785, 2022). "The silencing of BTLA or its ligand HVEM promotes cell proliferation via the ERK1/2 pathway, suggesting that tumor cell-intrinsic BTLA/HVEM is a potential tumor suppressor and is likely to have a potential antagonist for immunotherapy." (PMID 36552785, 2022). "Tfh cells in metastatic TME highly express BTLA which was reported to be an inhibitory molecule on lymphocytes, hindering lymphocyte development and suppressing tumor immunity." (PMID 36148946, 2022). "The results showed that overexpression of BTLA in the HVEM KD cells abolished the inhibitory effect of BTLA on tumor cells." (PMID 36552785, 2022). "There are reports that depending on the tumor microenvironment, the action of BTLA varies, hence its different expression depending on the tumor type." (PMID 35204342, 2022). "Clearly, the molecular understanding of BTLA is mainly confined to the interaction between the immune cells and tumor cells." (PMID 36552785, 2022). "As for T cell exhaustion, notable negative relationship between FXYD2 expression and CTLA-4, TIGIT, and BTLA persisted before and after tumor purity adjustment." (PMID 36313180, 2022). "This study demonstrates that tumor cell-intrinsic BTLA/HVEM is a potential tumor suppressor and is likely to have a potential antagonist for immunotherapy, thus representing a potential biomarker for the optimal cancer immunotherapeutic treatment." (PMID 36552785, 2022). "Collectively, these data indicate that there is difference between different BTLA expression subpopulations, and tumor-intrinsic BTLA is a potential tumor suppressor." (PMID 36552785, 2022). "HVEM is the only reported ligand for BTLA and is expressed on tumor cells to mediate immune tolerance, and the ligation of BTLA and HVEM can negatively regulate the proliferation of lymphocytes." (PMID 36552785, 2022).
tumor (continued). "In vivo breast carcinoma models have shown the effectiveness of antibodies against BTLA in controlling tumor growth and metastasis, accompanied by an increase in the number of NKT cells and the expression of cytotoxicity marker genes." (PMID 36140182, 2022). "B and T lymphocyte attenuator (BTLA) is an immune checkpoint molecule that mediates the escape of tumor cells from immunosurveillance." (PMID 36552785, 2022). "At the same time, the expression levels of cytokines and immunosuppressor molecules (PD1, PD-L1, PD-L2, CTLA4, TIGIT, TIM-3, BTLA, and LAG3) were significantly higher in low-risk groups, implying more tumor immunogenicity in the low-risk group." (PMID 36217201, 2022). "Studies have examined the role of anti-BTLA antibodies in tumor, inflammatory diseases, and transplantation rejection." (PMID 33859648, 2021). "BTLA is mainly expressed in pulmonary carcinoma cells but shows low expression in tumour-infiltrating lymphocytes." (PMID 34631565, 2021). "In contrast, BTLA is upregulated upon T cell activation, increasing the susceptibility of T cells to inhibition by HVEM+ tumor cells." (PMID 34208480, 2021). "The findings show that BTLA-neutralizing antibodies can inhibit tumor development, while agonistic anti-BTLA antibody treatment reduces inflammation and prolongs allograft survival." (PMID 33859648, 2021). "In contrast, BTLA was expressed at low (normalized log2 counts < 3) and similar levels in the tumor and patient-matched normal tissues." (PMID 34208480, 2021). "Based on our data, we propose that BTLA can be a target of tumor immunotherapy alone or in combination with anti-CD47." (PMID 34885092, 2021). "NanoString immune profiling of tumors confirmed that reovirus increased tumor immune cell infiltration and revealed an upregulation of the immune-regulatory receptor, B- and T-lymphocyte attenuator (BTLA)." (PMID 33665363, 2021). "In concordance with these data, we identified a population of bystander BTLA+ CD4+ T cells in proximity to tumor cells." (PMID 34885092, 2021). "In FL, transformation to DLBCL and lower OS was associated to diminished BTLA expression and augmented HVEM expression on tumor cells." (PMID 33917094, 2021). "BTLA regulates the immune system by inhibiting T cell reactions and restricting cytokine production and creates a tumor microenvironment that suppresses immune responses." (PMID 34940257, 2021). "PD-1 and BTLA are evolutionarily related and are co-expressed on human and mouse tumor antigen-specific CD8+ T cells." (PMID 34966384, 2021). "BTLA mRNA levels were significantly lower in cancerous tissues, as well as in paired tumor and normal samples." (PMID 32793631, 2020). "In multivariable Cox regression, there were statistically significant differences between age, tumor size, regional lymph nodes metastasis, radiation therapy, and BTLA expression for OS and DSS prognosis." (PMID 33718105, 2020). "Most gene makers of NK cells showed mild and moderate correlations with BTLA expression in our research, supporting that BTLA limited anti-tumor immunity through type I NKT cells." (PMID 32793631, 2020). "BTLA is another inhibitory checkpoint receptor shared by both DC and T lymphocytes that can contribute to the dysfunction of tumor‐specific T cell responses." (PMID 32508018, 2020). "This pathway is manipulated by tumor cells by stimulating the production of the dysfunctional phenotype of T cells that constantly express BTLA that makes T cells inactivate." (PMID 33167514, 2020). "The gene enrichment functional process of BTLA further led to the analysis of the fractions of tumor-infiltrating immune cells (TIICs) in the tumor microenvironment (TME)." (PMID 33718105, 2020).
tumor (continued). "In the univariate Cox regression model, age, tumor size, regional lymph nodes, radiation therapy, and BTLA expression were significant prognostic factors relevant to OS and DSS (p < 0.05)." (PMID 33718105, 2020). "Inhibition of BTLA combined with chemotherapy can elevate immune activation and generate potent anti-tumor effects." (PMID 31753019, 2019). "Alterations in percentages of BTLA+CD19hi B lymphocytes in splenocytes and TACs of ascites revealed the role of BTLA expression in tumor progression." (PMID 31753019, 2019). "The mice treated with anti-BLTA Ab alone showed significant anti-tumor activities, which is resulted from inhibition of BTLA-mediated immunosuppression." (PMID 31753019, 2019). "All mice treated with paclitaxel and anti-BTLA Ab 20 μg/mouse and 40% of mice treated with paclitaxel and anti-BTLA Ab 10 μg/mouse were still alive even 100 days after the WF-3/Luc tumor challenge (p < 0.001, log-rank test)." (PMID 31753019, 2019). "All of the mice treated with paclitaxel and anti-BTLA Ab, paclitaxel, anti-PD-1 Ab and anti-BTLA Ab, or paclitaxel, anti-PD-L1 Ab and anti-BTLA Ab were alive 100 days after tumor challenge." (PMID 31753019, 2019). "Blocking BTLA-HVEM interaction leads to a decrease in suppressor T-cells in the tumor microenvironment and enhances antitumor immunity." (PMID 31027331, 2019). "The combination of chemotherapy and anti-BTLA Ab significantly reduced peritoneal tumor volumes and extended survival of tumor-bearing mice." (PMID 31753019, 2019). "Splenocytes from the tumor-bearing mice undergoing chemotherapy, incubated with anti-BTLA Ab, demonstrated greater cytotoxic effects." (PMID 31753019, 2019). "The ability of BTLA to inhibit tumor-specific human CD8+ T cells suggests it as a target for cancer immunotherapy." (PMID 31405076, 2019). "The combination of chemotherapy and anti-BTLA Ab for inhibiting BTLA significantly reduced peritoneal tumor volumes and extended survival of tumor-bearing mice." (PMID 31753019, 2019). "The combination of chemotherapy and anti-BTLA antibody for inhibiting BTLA significantly reduced peritoneal tumor volume and extended survival in tumor-bearing mice." (PMID 31753019, 2019). "The concentrations of pro-inflammatory cytokines such as IL-12, TNF-α, and IFN-γ were higher in the ascites of tumor-bearing mice receiving chemotherapy combined with anti-BTLA Ab (Fig. 2f1-f3)." (PMID 31753019, 2019). "Sixty percent of mice treated with bevacizumab and anti-BTLA Ab and 40% of mice treated with olaparib and anti-BTLA Ab were still alive 100 days after tumor challenge." (PMID 31753019, 2019). "Compared to those of naive mice spleen CD8+ T cells, the levels of PD-1, TIM-3, BTLA and Foxp1 were upregulated in tumour-bearing mice." (PMID 31594465, 2019). "HVEM, the ligand of BTLA, was expressed at high levels on immune cells in PyMT-tumors and at lower variegated levels on tumor epithelial cells, allowing the engagement of BTLA by several cells in the microenvironment of PyMT tumors." (PMID 29518903, 2018). "In the recent study, we observed a significantly increased BTLA expression on tumor-infiltrating CD4+ T cells in HCC patients." (PMID 30116751, 2018). "In our study, downregulating the expression of BTLA by a monoclonal antibody on tumor-infiltrating NKT cells induced protective immunity, likely due to the expansion of NK1.1+ T cells, as well as, or including, type I NKT cells." (PMID 29518903, 2018). "It remains to be tested which of the mentioned T cell subsets contribute mainly to the observed tumor control upon anti-BTLA treatment." (PMID 29518903, 2018). "The BTLA/HVEM pathway has been identified as a critical regulator in tumor immunity, but its dynamic changes in peripheral blood T cell subsets and their clinical significance are largely unclear in human malignancies." (PMID 30116751, 2018).
tumor (continued). "Future studies are warranted to further explore the translational values of the BTLA/HVEM pathway as therapeutic targets in various tumor types." (PMID 30116751, 2018). "We previously showed that increased BTLA expression on tumor-infiltrating CD4+ T cells contributes to T cell suppression in tumor in situ." (PMID 30116751, 2018). "Taken together, these data support a role of BTLA on type I NKT cells in limiting anti-tumor immunity." (PMID 29518903, 2018). "Consistently, our previous studies demonstrated that BTLA expression significantly increased on tumor-infiltrating CD4+ T cells which suppressed cytokine production in HCC patients." (PMID 30116751, 2018). "Loss of activity of human CAR-T cells against tumor cells in NSG mice or humans was associated with expression of multiple inhibitory receptors including PD-1, BTLA, LAG3, TIM3, and 2B4." (PMID 28239463, 2017). "A variety of other combinations with immune inhibition [such as with LAG-3, TIM-3, BTLA, etc.], chemotherapeutic agents and irradiation—as additive or designed to make a tumor more “antigenic”, etc., are in the drawing board." (PMID 28497159, 2017). "BTLA is expressed at a high level by tumor-reactive CD8 T cells and interaction with its ligand, HVEM, can inhibit the functional activity of this population." (PMID 25763356, 2015). "BTLA and PD-1 are co-expressed on tumor-specific CD8 T cells in melanoma patients and these cells are dysfunctional." (PMID 26347741, 2015). "We have previously shown that the type of vaccination impacts on the expression of BTLA and that tumor-specific T-cells after vaccination express multiple inhibitory receptors." (PMID 22347406, 2012). "However, as tumors progress, BTLA expression is often upregulated on tumor-infiltrating lymphocytes and tumor cells, contributing to immune exhaustion and facilitating immune escape." (PMID 41471273, 2025). "However, the upregulated expression of BTLA has also been reported on tumor-infiltrating lymphocytes (TILs), while HVEM is found on tumor cells." (PMID 41319234, 2025). "In addition, we analyzed the effects of combined blockade of BTLA and PD-1 on tumor growth and microenvironment." (PMID 40463377, 2025). "However, other research indicates that BTLA can inhibit tumor-specific CD8+ T cells, potentially compromising anti-tumor immunity." (PMID 39796775, 2025). "Furthermore, we investigated expression and distribution of BTLA on lymphocytes in tumor microenvironment of different specimens from NSCLC patients." (PMID 40463377, 2025). "In these settings, BTLA may act in concert with chemokine dysregulation, angiogenic factors, and fibroblast-derived barriers to limit immune accessibility to the tumor." (PMID 41471273, 2025). "Soluble BTLA (sBTLA) and PD-1 expression in OSCC is over four times higher compared to normal tissues, positively correlates with susceptibility to OSCC and significantly negatively correlates with OS and tumour mutation burden (TMB)." (PMID 40994140, 2025). "Given the complex interplay between B cells and other immune populations in cancer, targeting BTLA in B cells may provide a two-fold therapeutic benefit: restoring tumor-specific humoral immunity and reducing Breg-mediated immune suppression." (PMID 41471273, 2025). "Targeting BTLA may restore effector immune cell function, reprogram the tumor microenvironment, and enhance anti-tumor responses, particularly when combined with other immune checkpoint inhibitors such as PD-1 or CTLA-4." (PMID 41471273, 2025). "Beyond NK cells, BTLA is also expressed on other immune subsets relevant to tumor immunity." (PMID 41471273, 2025). "BTLA+ Tregs may exhibit enhanced suppressive capacity, while BTLA+ B cells and DCs tend to exhibit impaired antigen presentation and costimulatory function, thereby limiting the priming and activation of new tumor-specific T cells." (PMID 41471273, 2025).
tumor (continued). "In addition, the percentage of BTLA+CD8+ T cells in malignant pleural effusions was correlated with the CEA concentration, and the proportion of BTLA+CD8+ T cells in peripheral blood and tumors was associated with tumor size in NSCLC patients." (PMID 40463377, 2025). "BTLA may indirectly promote angiogenesis and lymphangiogenesis through its immunosuppressive effects within the tumor microenvironment." (PMID 41471273, 2025). "Through its interaction with HVEM, BTLA delivers potent inhibitory signals that modulate T cell, B cell, NK cell, and other immune subset activities, thereby contributing to immune evasion and tumor progression." (PMID 41471273, 2025). "In contrast, BTLA exhibited a significantly reduced expression in TILs compared to PBMCs (PBMCs: 32.4%; TILs: 22.6%), suggesting a distinct pattern of regulatory receptor modulation within the tumor microenvironment." (PMID 41300994, 2025). "PD-1 and BTLA represent 2 key immune inhibitory checkpoints in tumor immune evasion." (PMID 40985894, 2025). "Importantly, the relative contribution of NK cells versus other BTLA-expressing innate cells to tumor progression likely varies across cancer types and disease stages." (PMID 41471273, 2025). "Such structural and functional versatility translates into therapeutic potential, as BTLA blockade could complement existing checkpoint inhibitors and restore anti-tumor immunity in cancers resistant to PD-1 or CTLA-4 targeting therapies." (PMID 41471273, 2025). "Therefore, BTLA emerges as a promising therapeutic target and prognostic marker in cancer, with its modulation offering potential avenues for enhancing anti-tumor immune responses and improving clinical outcomes." (PMID 38233898, 2024). "BTLA expression seems to be regulated differently in various tumor entities." (PMID 38928307, 2024). "Abnormal BTLA expression, particularly within the tumor microenvironment (TME) and specifically on tumor-infiltrating lymphocytes (TILs), has been observed in diverse cancers and is frequently associated with impaired anti-tumor immune responses." (PMID 38233898, 2024). "Furthermore, BTLA + CD4 + T-cells produced less IL-2 compared to those from healthy mice, while BTLA + CD8 + T-cells in tumor- bearing mice had impaired IL-2 and TNF production." (PMID 38233898, 2024). "This suggests that increased BTLA expression may modulate the tumor EMT through the inflammatory microenvironment." (PMID 38233898, 2024). "In Lin’s study, it has emerged that resveratrol downregulates the thyroid hormones modulating the activities of PD-L1 and BTLA (two checkpoint-co-inhibitor receptors expressed on the surface of the immune system cell that when overexpressed participate in the tumor cells proliferation)." (PMID 38247942, 2024). "In tumor cells, the binding of BTLA to HVEM inhibits T cell activation and proliferation." (PMID 38254772, 2024). "Several checkpoint and inhibitory receptors, such as PD-1 (gene name: PDCD1), CTLA4, TIM-3 (HAVCR2), LAG3, CD39 (ENTPD1), CD160, KLRG1, CD96, BTLA, 2B4, and TIGIT, have been implicated in the reduction of immune activity and response in the tumor micro-environment." (PMID 39513882, 2024). "Noteworthy, ibrutinib improves CLL-associated T cell dysfunction and downregulates BTLA expression on tumor cells without affecting its expression on T lymphocytes." (PMID 37041226, 2023). "Moreover, evidence has displayed that miR-149-3p can regulate the expression of PD-1, TIM-3, and BTLA by binding to the 3′UTRs of their mRNAs, thereby preventing tumor immune escape." (PMID 36765782, 2023).